BCL2 (BCL2 apoptosis regulator)
Diseases named in the same sentence as BCL2 in open-access papers (continued):
Sharing a sentence is not in itself a finding about the gene and the disease.
glioma (continued). "Glioma-related oncogene homolog 1 (Gli1) was originally named in glioma research, which can affect glioma cell apoptosis and proliferation via regulated cyclin D1 and Bcl-2." (PMID 35874843, 2022). "Etoposide induces apoptosis of glioma cells by successively generating ceramide, modulating Bax/Bcl-2, releasing cytochrome C, and activating caspase." (PMID 36268515, 2022). "In line with this, a polymeric micelle prepared based on a folate-conjugated triblock copolymer of poly (ε-caprolactone) (PCL), PEI, and PEG has been developed to carry TMZ and Bcl-2 siRNA for gliomas treatment." (PMID 35874843, 2022). "The Akt pathway is also suppressed by Ole (200/400 μM) in in vitro glioma cells, which are accompanied by regulating Bax, Bcl2, MMP-2, and MMP-9, which favor the apoptosis pathway." (PMID 36013319, 2022). "According to some research, the expression of Bcl-2 in glioma tumors is elevated compared with normal astrocytes." (PMID 35795095, 2022). "It was reported that gga-miR-30c-5p inhibited glioma proliferation and invasion via targeting Bcl-2 and regulated cisplatin-induced apoptosis of renal tubular epithelial cells via targeting Bnip3L and Hspa5." (PMID 35632731, 2022). "miR-519a improves chemosensitivity and enhances autophagy in glioma by targeting STAT3/Bcl2 signaling." (PMID 35432536, 2022). "CRNDE promotes glioma malignancy by acting as ceRNA and blocking the downregulation of Bcl-2 and Wnt2 mediated by miR-136-5ps (Li D.-X." (PMID 35359593, 2022). "There have been several studies conducted with various Bcl-2 inhibitors and their effects on glial tumors." (PMID 36309485, 2022). "The induction of apoptosis, modulation of Bax/Bcl-2 signaling ratio, and cell cycle arrest at G0/G1 phase of cell cycle seems to be the possible mechanism of action of sugiol in glioma cells." (PMID 35677372, 2022). "In DBTRG glioma cells, the action of curcumin increases the expression of Bax and caspase 3 and reduces the expression level of Bcl-2, inducing apoptosis through an intrinsic pathway." (PMID 36268515, 2022). "miR-519a promotes chemosensitivity and enhances autophagy of glioma cells by regulating STAT3/Bcl2 signaling." (PMID 35432536, 2022). "When cisplatin-resistant U87 cells interact with CIK, the expressions of MDR-1, MRP-1, GST-π, and Bcl-2 are all down-regulated, thus reversing the drug resistance of gliomas." (PMID 35674307, 2022). "Gossypol (AT-101) tested in GBM treatment, binds to BH3 domains of Bcl-2, Bcl-xl, and Mcl-1, and is reported to efficiently inhibit in vitro and in vivo growth of glial tumors." (PMID 36309485, 2022). "The increase in BAX/Bcl‐2 ratio is thought to contribute to the sensitivity of glioma cells to anticancer therapy by activating the apoptotic cascade." (PMID 35703405, 2022). "This prevents the combination of Cul3-based E3 ligase and Bcl2, thereby maintaining the stability of Bcl2 and increasing the resistance of glioma cells to oxidative stress-induced apoptosis." (PMID 35935861, 2022). "Downregulation of the PI3K/AKT pathway can restrain the expression of a variety of downstream molecules, such as Cyclin D1 and Bcl-2, thereby inhibiting the proliferation and enhancing the apoptosis of glioma cells." (PMID 36147923, 2022). "Dose-dependent reduction of Bcl-2 expression and elevation of Bax expression further confirmed the promoting effect of Sal A on the apoptosis of glioma cells." (PMID 35505656, 2022). "Particularly, the authors found that temozolomide glioma resistant-cells secrete higher levels of Cx43 in sEVs promoting an increase in proliferation and Bcl-2 expression but reducing Bax and cleaved-caspase 3 in target cells." (PMID 35931686, 2022). "In our recent work, we have shown, that Hyp presence in human endothelial and glioma cells resulted in significant light-independent effects on ultrastructure, mitochondria function and metabolism, and Bcl2 proteins’ distribution and synthesis." (PMID 36267274, 2022).
glioma (continued). "The induction of apoptosis was shown to be the possible mechanism mediating the antiproliferative effects of sugiol against glioma cells as suggested by nuclear deformation and modulation of Bax/Bcl-2 signaling ratio." (PMID 35677372, 2022). "The over-expression of miR-133b causes glioma cells to increase their apoptosis by reducing N-cadherin, Vimentin, MMP-2 and Bcl-2 and elevating Bax, cleaved Caspase-3 and PARP expression." (PMID 35111757, 2021). "For example, TUG1 can promote tumor cell apoptosis and inhibit the growth of glioma by activating caspase 3- and caspase 9-mediated proapoptosis, inhibiting bcl-2 mediated antiapoptosis." (PMID 33747256, 2021). "After the treatment with anti-glioma steroid, the expression of Bcl-2 proteins was dose-dependently decreased whereas expression of Bax protein was accumulated in increasing concentrations." (PMID 34440090, 2021). "In terms of glioma cell proliferation, the B-cell lymphoma/leukaemia-2 gene (bcl-2) plays an important role in tumour cell anti-apoptosis, promotes tumour cell proliferation, and inhibits tumour cell apoptosis." (PMID 34425834, 2021). "NLGN3 resulted in upregulated Bcl-2 and downregulated Bax in glioma cells, which suggested that the mitochondrial-dependent apoptosis pathway was inhibited." (PMID 34485271, 2021). "In malignant glioma, treatment with subtoxic doses of daidzein in combination with TRAIL induces rapid apoptosis in glioma cells because daidzein overcomes TRAIL resistance by modulating the expression of the intrinsic apoptotic inhibitor bcl-2." (PMID 34540371, 2021). "This suggested that LINC01087 acted as miR-384 sponge, regulated Bcl-2 to inhibit the growth of glioma cells and induced apoptosis, which was a potential target of glioma." (PMID 34459789, 2021). "Bcl-2 is an apoptosis inhibitor, but bax is an apoptosis inducer; hence, the determination of bcl-2 and bax levels can be used as a crucial judge of the malignancy of gliomas." (PMID 34556140, 2021). "Knockdown of SNHG16 suppresses the viability of glioma cells and promotes apoptosis by regulating the expression of B-cell lymphoma 2 family (Bcl-2) proteins and activating the PI3K/Akt signaling pathway." (PMID 33980320, 2021). "In fact, treatment of C6 glioma cells with 25 μM Cl-IB-MECA reduced Bcl-2 expression and increased caspase-3 activity after 24 h of treatment." (PMID 34539333, 2021). "Then, Western blot analysis was performed to investigate the effect of curcumin on cyclin D1, CDK4/6, Bcl‐2 and Bcl‐XL in glioma cells." (PMID 34169637, 2021). "In particular, miR-16 in glioma cells was upregulated negatively influencing the cell B cell CLL/lymphoma 2 (BCL2)/NFkB/Matrix Metallopeptidase 9 (MMP9) axis." (PMID 33672251, 2021). "Similar to our result, the combination treatment with PAC and ATRA was shown to promote the apoptosis of U87MG glioma cells through the inactivation of Bcl-2 and upregulation of activated caspase-8 expression." (PMID 34660779, 2021). "In the present study, the combination of sorafenib and TMZ obviously decreased the mitochondrial membrane potential of glioma cells and increased the Bax/Bcl-2 ratio and cytosolic cytochrome c release." (PMID 34277607, 2021). "After transfecting glioma cell lines with ANRIL and SOX9 inhibitory sequences, we measured apoptosis-related proteins (bcl-2 and bax) to observe changes in multiplication, invasion, and apoptosis in glioma cell lines." (PMID 34556140, 2021).
glioma (continued). "By targeting miR-139-3p which downregulates cyclin D1, c-Myc and Bcl2, and upregulates Bax, CircKIF4A suppression can improve apoptosis in glioma cells." (PMID 35111757, 2021). "We found that the nuclear aggregation of AIF was consistent with the upregulation of Bax and the downregulation of Bcl-2 in U251 glioma cells." (PMID 34277607, 2021). "Firstly, repaglinide possesses cytotoxic effects against hepatic, breast and cervical carcinoma cells (HepG2, MCF-7 and HeLa cells), or reduces the expression of Bcl-2, Beclin-1 and PD-L1 in glioma tissues." (PMID 33382703, 2020). "We previously reported that indomethacin-induced glioma apoptosis was rarely accompanied by protein level change of Bax, Bad, Bid, and Bcl-2." (PMID 31952288, 2020). "Clinical examination has revealed an elevated expression of Bcl-2 anti-apoptosis family proteins in malignant glioma, implying a crucial role of apoptosis inactivation in glioma drug resistance, poor prognosis, and recurrence." (PMID 31952288, 2020). "In glioma, knockdown CRNDE induced cancer cells apoptosis and then decreased Bcl2/Bcl2-associated X protein (Bax) ratio through different pathways." (PMID 32435153, 2020). "In comparison with non-TBI neurosurgical controls, i.e., patients undergoing epilepsy and glioma resections, Bcl-2 expression is greater after head injury, ranging from 2.9-fold to 17-fold." (PMID 32570722, 2020). "In our study, we have found that CFTR up‐regulates Bcl2 more than Bax via PI3K/Akt pathway, thus decreases the ratio of Bax/Bcl2 and makes the glioma cells less susceptible to apoptotic signals." (PMID 32463592, 2020). "MiR-16 and miR-136 increase the sensitivity of glioma cells to temozolomide by targeting Bcl-2 and AEG-1, respectively." (PMID 32820249, 2020). "IKBKE knockdown in glioma cells decreased Bcl‐2 expression and promoted cleavage and activation of caspase‐3, which suggested that IKBKE induced glioma cell resistance to apoptosis." (PMID 31733040, 2020). "Another study indicated that autophagy is induced by blocking the interaction between Bcl‐2 and Beclin1, as a result of BH3 mimetic S1 promoting autophagy via blockade of Bcl‐2/Beclin1 interaction in human glioma cells." (PMID 32239627, 2020). "Our results clearly indicate that CFTR promotes glioma development via Akt/Bcl2‐mediated anti‐apoptosis pathway." (PMID 32463592, 2020). "Hypericin also alters the distribution of Bcl-2 in U-87 MG glioma cells and in human coronary aorta endothelial cells." (PMID 33680035, 2020). "The down‐regulation of Bcl‐2 and up‐regulation of Bax following bortezomib treatment indicate that the apoptotic process was activated in the treated glioma cells, thus mediating an anti‐tumour effect, and inhibition of PLK4 further enhanced this effect." (PMID 32126150, 2020). "Reports show that miR-30b-5p inhibits human colorectal cancer by targeting KRAS, PIK3CD and BCL2 and modulates glioma cell proliferation by directly targeting MTDH." (PMID 32586272, 2020). "Taken together, based on our findings and previous study, it is plausible that CFTR promotes glioma progression via up‐regulation of Akt/Bcl2‐mediated anti‐apoptosis pathway." (PMID 32463592, 2020). "The results of the present study show that diosmetin effectively promotes apoptosis, downregulates the levels of Bcl-2, and elevates the levels of Bax and cleaved caspase-3 in glioma cells." (PMID 31906574, 2020). "Mechanistically, KLHDC8A regulated various functions in glioma by directly mediating Bcl2, BAX, p21, CDK2, MMP2 transcription and ERK and P38 MAPK activation." (PMID 32851798, 2020). "After determining the relationship between ALO and solid tumors, we further investigated the effect of ALO on the inhibition of Bcl2 in glioma cells." (PMID 31534865, 2019).
glioma (continued). "Overexpression of Cx43 reduced the levels of anti-apoptotic Bcl-2, and thus enhanced paclitaxel- or etoposide-induced apoptosis of U251 and T98G glioma cells." (PMID 30642339, 2019). "Our findings discover that SAE1 overexpression leads to increase of Akt SUMOylation and Akt phosphorylation (Ser473), which increases expression of CDK2, Cyclin D1, Bcl-2 and ultimately to promote glioma cell proliferation and progressin." (PMID 31345225, 2019). "Protein levels of Bcl2 were obviously higher in U118 and SK-N-AS compared to T98G, U87, U251 and Hs683 glioma cells." (PMID 31534865, 2019). "Treatment of the human grade IV glioma cells with 1.5 mg mL−1 MtRV extract significantly decreased the mRNA level of Bcl-2 (p < 0.05)." (PMID 30610508, 2019). "Taken together, these findings suggest that the natural agent ALO effectively enhances apoptosis by acting as a potential Bcl2 inhibitor in human glioma cells." (PMID 31534865, 2019). "Both TMZ and AP-2α synergistically inhibited the growth and induced the apoptosis of glioma cells, accompanied by decreased levels of Bcl-2, Pro Caspase-3 and the stem cell markers Nanog and Sox2 in a dose-dependent manner." (PMID 31534499, 2019). "DMAMCL reduces tumor proliferation via down-regulating anti-apoptosis gene Bcl2 and increasing apoptosis in a dose-dependent manner in glioma cells in vitro and in vivo." (PMID 30850026, 2019). "In our study, we found that ZHX1 similarly exerted a regulator role on glioma cell apoptosis and promoted glioma cell survival via upregulation of Bcl-2 and downregulation of Bax." (PMID 31648104, 2019). "In glioma cells, miR-873 overexpression results in the decrease of Bcl-2, followed by suppressing cell proliferation, motility and promoting apoptosis in cells which are cisplatin resistant." (PMID 31289617, 2019). "Overexpression of cytoplasmic Cx43 in U251 and T98G glioma cells reduced the levels of anti-apoptotic Bcl-2." (PMID 30642339, 2019). "The decreased levels of Bcl‐2 and increased levels of Bax indicated that olanzapine induced apoptosis in glioma cells." (PMID 30955240, 2019). "Similar to the investigation in malignant lymphoid cells, we observed that SRT2183 also halts the mitotic cycle and cellular demise in glioma cell lines accompanied by an increase of Bim and decrease of Bcl-2 and Bcl-xL." (PMID 31319814, 2019). "We further demonstrate that the improved CD-NSC survival afforded by transient Bcl-2 overexpression results in decreased tumor burden in an orthotopic xenograft glioma mouse model following administrations of intracerebral CD-NSCs and systemic prodrug." (PMID 30026762, 2018). "Our data reveals that the formed Au DENPs-β-CD carrier enables efficiently delivery of siRNA to glioma cells, has good cytocompatibility once complexed with the siRNA, and enables enhanced gene silencing to inhibit the expression of Bcl-2 and VEGF proteins." (PMID 29495429, 2018). "Down-regulation of Bcl-2 or Bcl-XL results in glioma cell death and sensitization to chemotherapy and radiotherapy." (PMID 30587839, 2018). "As2O3 significantly inhibited expression of the anti-apoptotic gene Bcl-2 and upregulated the pro-apoptotic gene Bax in both C6 and 9 L glioma cells in a time-dependent manner." (PMID 29610575, 2018).
glioma (continued). "In line with previous studies implying the role of BCL2 in radiotherapy insensitivity, we thus suggest that miR-153-3p enhances radiation sensitivity of glioma cells through targeting BCL2." (PMID 30537994, 2018). "Preliminary our data suggest that the single administration of Tinostamustine is more active in glioma cells with lower basal levels of Bcl2 (manuscript in preparation)." (PMID 29486795, 2018). "As2O3 significantly inhibited the expression of the anti-apoptotic gene Bcl-2, and upregulated the proapoptotic gene Bax in both C6 and 9 L glioma cells in a time-dependent manner." (PMID 29610575, 2018). "To further elucidate the role of Bcl2 in increased radio-sensitivity we performed clonogenic experiments on glioma cell cultures by administration of fixed 5 μM AT101." (PMID 29486795, 2018). "NF-κB regulates the transcription of cyclin D1 (an important factor for G1 progression and G1/S transition) and Bcl-2 (anti-apoptotic gene) in glioma cells." (PMID 29410396, 2018). "Previous studies have reported that 5 μM BIX inhibited the proliferation and induced apoptosis through downregulation of Bcl-2 expression and upregulation of Bax expression in U251 glioma cells." (PMID 29531826, 2018). "Contrarily, in glioma cells the antiapoptotic BCL-family member BCL-2 protects against cell death induced by chemotherapy." (PMID 30224928, 2018). "In our study, the results showed that flubendazole increased apoptosis among glioma cells via downregulating the expression of Bcl-2, Bcl-xl, and PARP-1, while upregulating the expression of caspase-3, caspase 6 and caspase-9." (PMID 29531815, 2018). "It has been reported that glioma tumors have elevated levels of the anti-apoptotic proteins Bcl-2 and reduced levels of the apoptotic protein Bax, giving rise to a predisposed anti-apoptotic state correlated with resistance to chemotherapy." (PMID 30583528, 2018). "It is widely accepted that caspase-3 is the final executioner phase of apoptosis, indicating that miR-153-3p induces glioma cells apoptosis via BCL2/caspase-3 pathway." (PMID 30537994, 2018). "In the preclinical studies using an antisense approach, downregulation of BCL-2 or BCL-XL resulted in glioma cell death and sensitization to the effects of chemotherapy and radiotherapy." (PMID 29977208, 2018). "An increase in caspase-3 activity indicates increased apoptosis when CCNG2 is overexpressed in the glioma cell lines and Bcl-2 is downregulated." (PMID 29720957, 2018). "Further analysis indicated the expression of BCL2 mRNA in clinical samples revealed that the level of BCL2 mRNA was higher in radioresistant glioma tumors compared with that in radiosensitive tumors." (PMID 30537994, 2018). "The ARE-binding protein HuR (human antigen R) has been reported to bind to the 3′ UTRs of MCL1, BCL2, and BCLxL, stabilizing their RNA, and increasing their expression in glioma." (PMID 29361709, 2018). "Further bioinformatics analyses using TargetScan, miRanda, and DAVID identified Bcl-2 and Wnt2 as downstream targets of miR-136-5p in gliomas." (PMID 29152149, 2017). "We therefore propose that CRNDE functions as a competing endogenous RNA (ceRNA) that binds to and negatively regulates miR-136-5p, thereby protecting Bcl-2 and Wnt2 from miR-136-5p-mediated inhibition in glioma." (PMID 29152149, 2017). "On the other hand, TFAP2A, B genes, known tumor suppressor genes, participate in the reduction of glioma progression, by downregulation of Bcl-xl, Bcl-2, c-IAP2, and survivin." (PMID 29119102, 2017). "Our results suggest that CRNDE functions as a ceRNA to promote glioma malignancy by indirectly inducing Bcl-2 and Wnt2 expression through binding and repression of miR-136-5p." (PMID 29152149, 2017).